RETN (resistin)
Diseases named in the same sentence as RETN in open-access papers (continued):
Sharing a sentence is not in itself a finding about the gene and the disease.
lung cancer (14 papers, 2010 to 2025). A malignant neoplasm involving the lung. "In a separate study on RETN polymorphisms, 227 lung cancer patients who underwent at least two cycles of chemotherapy were included." (PMID 40002704, 2025). "The present study delves into the relationship between resistin expression and genetic polymorphisms with cancer risk and clinical outcomes among lung cancer patients undergoing platinum-based chemotherapy." (PMID 40002704, 2025). "Unconditional logistical regression analysis was employed to evaluate the associations between RETN polymorphisms and lung cancer risk, as well as clinical outcomes." (PMID 40002704, 2025). "In the present study, we aimed to investigate the correlation between resistin expression and polymorphisms with overall survival in lung cancer patients." (PMID 40002704, 2025). "We conducted a hospital-based case–control study to analyze the genotypes of resistin polymorphisms and explored their association with lung cancer risk, efficacy, and toxicity in lung cancer patients receiving platinum-based chemotherapy." (PMID 40002704, 2025). "In our study, we delved into the potential impact of RETN polymorphisms on lung cancer risk and chemotherapy outcomes." (PMID 40002704, 2025). "To date, only a few studies have focused on the association between RETN SNPs and lung cancer susceptibility, as well as clinical outcomes in lung cancer patients undergoing platinum-based chemotherapy." (PMID 40002704, 2025). "It was reported that TLR4 is a functional receptor of resistin in lung cancer cell migration and invasion." (PMID 40860289, 2025). "In our study, we assessed the role of RETN SNPs in platinum-based chemotherapy outcomes in lung cancer patients." (PMID 40002704, 2025). "In our study, we investigated the impact of RETN SNPs on the progression of lung cancer and the clinical outcomes of lung cancer patients undergoing platinum-based chemotherapy." (PMID 40002704, 2025). "The following sections will discuss the mechanisms of action of leptin, adiponectin, Nesfatin-1, Resistin, chemerin, and visfatin in lung cancer bone metastasis." (PMID 38571500, 2024). "Recently, TLR4 was reported to be the functional receptor of resistin in cell migration and invasion in lung cancer, whereas nuclear factor (NF)-κB is the intracellular downstream effector mediating resistin-induced migration and invasion." (PMID 35135563, 2022). "RETN SNPs have been found to correlated with worsening disease in Chinese Han patients with lung cancer." (PMID 32226495, 2020). "Elevated levels of plasma resistin have been found in breast cancer and in non–small cell lung cancer patients." (PMID 21254741, 2010). "No substantial association was observed between RETN polymorphisms and lung cancer risk, chemotherapy response, or toxicities, except for rs1862513, which showed a link with severe gastrointestinal toxicity." (PMID 40002704, 2025). "We investigated the role of RETN rs1862513 and rs3745367 in lung cancer." (PMID 40002704, 2025). "However, extensive molecular research has demonstrated that resistin plays a crucial role in proliferation, metastasis, angiogenesis, inflammation, and metabolic regulation in cancer cells, including those of lung cancer." (PMID 40002704, 2025). "This review primarily explores the role of BMAs and their secreted adipokines (leptin, adiponectin, Nesfatin-1, Resistin, chemerin, visfatin) in lung cancer bone metastasis, aiming to provide new insights into the mechanisms and clinical treatment of lung cancer bone metastasis." (PMID 38571500, 2024). "Moreover, in a recent study, it was shown that mice receiving anti-resistin antibody had significantly decreased incidence of lung cancer development and metastasis." (PMID 25868978, 2015). "Previous studies have demonstrated that resistin is involved in the metastasis of breast and lung cancers; however, the role of resistin in chondrosarcoma is currently largely unknown." (PMID 25404641, 2015).
lung cancer (continued). "However, RETN SNPs did not exhibit a significant association with overall survival in lung cancer patients." (PMID 40002704, 2025). "Furthermore, evidence suggests that in patients with lung cancer, high serum resistin levels may play a role in the pathogenesis of cancer cachexia." (PMID 30406149, 2018).
acute coronary syndrome (13 papers, 2009 to 2026). Signs and symptoms related to acute ischemia of the myocardium secondary to coronary artery disease. "In patients with acute coronary syndromes, elevated levels of IL-1ra, resistin, and CRP were independently associated with greater lesion complexity, functional significance, and plaque vulnerability." (PMID 41226718, 2025). "The AR index, combined with adiponectin and resistin levels, is a cost-effective and a precise diagnostic biomarker for insulin sensitivity and is a predictor of acute coronary syndrome." (PMID 26930652, 2016). "In acute coronary syndromes, resistin levels surge significantly compared to stable CAD or controls, reflecting its role in plaque rupture and ischemia-driven inflammation." (PMID 41347124, 2025). "In another study, 220 patients with acute coronary syndrome (ACS) had significantly higher serum resistin concentrations than patients classified as normal." (PMID 27608037, 2016). "Furthermore, patients with acute coronary syndrome (ACS) showed high levels of resistin with enhanced resistin gene expression within the adipose tissue, in comparison to cases of stable angina." (PMID 28286779, 2017). "Moreover, patients who suffered acute coronary syndrome showed increased resistin levels in the early onset of the episode, suggesting that resistin may have a negative impact on plaque stability." (PMID 37238961, 2023).
liver fibrosis (13 papers, 2014 to 2025). "A higher degree of liver fibrosis in patients with viral hepatitis B was associated with significantly higher serum resistin concentrations." (PMID 35510200, 2022). "The mechanism of GLP-1RA on hepatic fibrosis can be attributed partly to the decrease in pro-inflammatory adipokines such as leptin, (monocyte chemoattractant protein-1and resistin, which are associated with the progression to NASH and fibrosis." (PMID 33897616, 2021). "Serum resistin levels are associated with non-alcoholic fatty liver disease, degree of liver fibrosis and degree of liver cirrhosis in humans." (PMID 33142854, 2020). "When using this list for an Ingenuity Pathway Analysis (IPA), “HMGB1 pathway” (p = 9.26 × 10−10) followed by “Hepatic fibrosis/Stellate cell activation” (2.68 × 10−09) was suggested as the two top canonical pathways associated with the RETN polymorphism." (PMID 31645609, 2019). "Further, resistin, a signaling molecule secreted from adipocytes and monocytes, is known to be involved in inflammatory processes, and has recently been reported to be associated with hepatic fibrosis." (PMID 24524410, 2014). "Adipokines such as TNF-α, leptin, and resistin can be disrupted by lower levels of thyroid hormone in circulation, exacerbating liver fibrosis." (PMID 40006040, 2025). "This study aimed to determine the relationship of serum adiponectin and resistin levels with the severity of liver fibrosis in patients with chronic hepatitis B (CHB), depending on the duration of antiviral therapy." (PMID 35510200, 2022). "A positive correlation was found between serum resistin levels and the degree of liver fibrosis (p<0.001)." (PMID 35510200, 2022). "Our study showed that the concentration of serum resistin in patients with chronic hepatitis B corresponds to the severity of liver fibrosis and depends on the duration of antiviral therapy." (PMID 35510200, 2022). "Serum concentrations of adiponectin and resistin were estimated with the ELISA method, while the degree of liver fibrosis was determined using FIB-4 and APRI score." (PMID 35510200, 2022). "A significant positive correlation was found between serum concentrations of resistin and liver fibrosis estimated based on the values of FIB-4 (r=0.741, p=0.001) and APRI score (r=0.839, p=0.001)." (PMID 35510200, 2022). "Altogether, the pro-inflammatory activities of resistin are harmful if left untreated, particularly with respect to accelerating hepatic fibrosis." (PMID 27477870, 2016). "Finally, RETN was found to have a pro-inflammatory role in HSCs, suggesting that RETN is involved in liver fibrosis; the serum levels of RETN were higher in NAFLD and were positively correlated with liver inflammation." (PMID 36397950, 2022). "Therefore, this study aimed to determine the importance of serum adiponectin and resistin levels as prognostic markers and indicators of the liver fibrosis stages in patients with CHB, depending on the duration of antiviral therapy." (PMID 35510200, 2022). "As opposite of that, there was a significant difference between serum resistin levels depending on the degree of liver fibrosis, according to the values of APRI score (4.82±1.11 ng/mL in APRI score <0.5 vs 8.98±3.08 ng/mL in APRI score 0.5-1.45 vs 17.45±3.96 in APRI score >1.45, p=0.001)." (PMID 35510200, 2022). "Furthermore, the serum resistin level is positively related to the severity of inflammation and liver fibrosis in NAFLD patients." (PMID 34603198, 2021). "Hepatic fibrosis is well known to be mediated by the RETN pathway." (PMID 31645609, 2019). "Indeed, we focused on the proteases involved in the degradation or modification of ECM (MMP-1 and TIMP-1), the products of ECM (collagen IA1) and fibrosis-related regulatory factors, such as PDGF-BB, TGF-β1, and resistin, all of whose essential roles in liver fibrosis have been established." (PMID 35715541, 2022).
liver fibrosis (continued). "The serum levels of resistin, TGF-β1, MMP-1, TIMP-1, collagen IA1 and PDGF-BB, which are markers that are known to be involved in the process of hepatic fibrosis, were assayed." (PMID 35715541, 2022). "Univariate two-way ANOVA test showed that progression of liver fibrosis estimated by FIB-4 and APRI scores had a significant effect on resistin values (F 17.42, p=0.001; F 40.09, p=0.001), as well as the length of antiviral treatment (F 8.109, p=0.031)." (PMID 35510200, 2022). "Progression of liver fibrosis estimated by FIB4 and APRI scores as well as the length of antiviral treatment had a significant effect on serum resistin values in CHB patients on antiviral therapy." (PMID 35510200, 2022). "Multivariate analysis revealed that waist-hip ratio, higher serum triglyceride, and hyperresistinemia were independent factors related to higher grade of steatosis; whereas hepatic resistin and serum cytokeratin predict NASH and severity of liver fibrosis." (PMID 24559185, 2014).
ovarian carcinoma (13 papers, 2013 to 2025). A malignant neoplasm originating from the surface ovarian epithelium. "It should be stressed that there are only a few indications in the literature that associate resistin with the progression of ovarian cancer." (PMID 35453670, 2022). "Moreover, there is also compelling evidence that resistin production is remarkably associated with ovarian cancer prognosis." (PMID 40076482, 2025). "In addition to its pivotal role in inflammation-related diseases, RETN was shown to suppress the miR-186-5p levels, thereby contributing to cancer resistance in ovarian cancer and facilitating VEGF-C-associated lymphangiogenesis in human chondrosarcoma cells." (PMID 36176750, 2022). "Resistin also plays a crucial role in angiogenesis because it was established that ovarian cancer cell lines treated with resistin exhibit an increase in VEGF production." (PMID 40076482, 2025). "Regarding the role of resistin on ovarian cancer cells, it enhances the proliferation of ovarian cancer cells by triggering the mammalian target of rapamycin kinase (mTOR) pathway and upregulating 70 kDa S6 kinase responsible for autophagy inhibition." (PMID 40076482, 2025). "Regarding the clinical significance of resistin on ovarian cancer, the current scientific reports indicate that resistin induces chemoresistance to cisplatin." (PMID 40076482, 2025). "The novel scientific reports also demonstrate that the resistin expression is enhanced in ovarian cancer tissues." (PMID 40076482, 2025). "Elevated resistin levels accompany chronic inflammation, which can induce the process of carcinogenesis in ovarian cancer." (PMID 37238197, 2023). "The exiting results have revealed that the higher level of resistin, the poorer prognosis of ovarian cancer." (PMID 37605299, 2023). "The current literature data still provide limited evidence directly linking the effect of resistin to the development of ovarian cancer." (PMID 35453670, 2022). "In ovarian cancer cells (HO-8910), resistin induced the expression of VEGF through the PI3K/AKT-Sp1 pathway." (PMID 36291097, 2022). "Perhaps in the future, resistin will become a prognostic, a predictor, or a target of therapy in obese patients with ovarian cancer." (PMID 35453670, 2022). "Other investigations have revealed that resistin stimulates the growth of ovarian cancer cells, increases their invasive potential, and enhances the secretion of the angiogenesis markers VEGF and MMP-2 by tumor cells." (PMID 35453670, 2022). "Tissue factors from the family of adipocytokines that regulate lipid metabolism such as adiponectin and resistin are expressed in ovarian cancer cells and can drive tumor progression." (PMID 36105223, 2022). "It has been shown in vitro that resistin stimulated the growth and differentiation of new cell colonies using ovarian cancer cell lines." (PMID 35453670, 2022). "It was shown in vitro that resistin stimulates the growth and differentiation of ovarian cancer cells." (PMID 35453670, 2022). "Based on these results, resistin appears to promote the proliferation of ovarian cancer cells through the mTOR signaling pathway." (PMID 34659568, 2021). "Exogenous resistin induced ovarian cancer cell proliferation, whereas rapamycin had the opposite effect." (PMID 34659568, 2021). "We further examined the effect of resistin on the proliferation and migration of ovarian cancer cells (SKOV3 and CAOV3 cells) and its primary mechanism of action." (PMID 34659568, 2021). "The observed resistance against cisplatin can be explained by our results that resistin increases stemness in ovarian cancer cells." (PMID 30131543, 2018). "We investigated a role of resistin in the growth, clonogenicity, invasion and cisplatin-resistance of ovarian cancer cells, and sought to elucidate the mechanistic details of such resistin-mediated effects." (PMID 30131543, 2018).
ovarian carcinoma (continued). "Our results provide first evidence for such oncogenic effects of resistin in ovarian cancer models and a rationale for future studies to further understand the mechanistic role of resistin in ovarian cancer invasiveness, metastasis and therapy resistance." (PMID 30131543, 2018). "Having established a definite role of resistin in ovarian cancer cells’ proliferation in vitro, we next sought to test the effect of resistin in vivo." (PMID 30131543, 2018). "It has been suggested that resistin can induce resistance against chemotherapy, and therefore, we next evaluated if resistin can, similarly, induce resistance against cisplatin in ovarian cancer cells." (PMID 30131543, 2018). "We establish a mechanistic role of miRNA-regulated EMT in the chemoresistance, and, thus, establish resistin as a potentially important target for possible intervention in advanced stage and relapsed ovarian cancers." (PMID 30131543, 2018). "In summary, we report, for the very first time, a role of resistin in invasion and chemoresistance of ovarian cancer cells." (PMID 30131543, 2018). "The novel research demonstrated that overexpression of microRNA (miRNA), e.g., pre-let-7a, pre-miR-200c, and pre-miR-186 attenuated resistin action in ovarian cancer, leading to epithelial-to-mesenchymal transition, which is a hallmark of cancer cell migration." (PMID 40076482, 2025). "In addition, it was shown that resistin positively correlates with tumor cell migration in ovarian cancer, contributing to ovarian cancer progression." (PMID 37190027, 2023). "Current reports indicate that abnormal expression of resistin and its receptors are found in the course of many malignancies, particularly breast cancer, esophageal squamous cell carcinoma, gastric cancer, endometrial adenocarcinoma and ovarian cancer." (PMID 37190027, 2023). "In addition, resistin influences the generation of the invasive character of ovarian cancer cells by inhibiting miRNAs let-7, miR-200c and miR-186." (PMID 37190027, 2023). "The experiment also proved that resistin promotes the migration of ovarian cancer cells." (PMID 35453670, 2022). "In addition, rapamycin inhibited the activity of 70-KDaS6 kinase (P70S6K) downstream of mTOR, demonstrating that resistin promotes the proliferation of ovarian cancer cells by activating mTOR." (PMID 34659568, 2021). "Overall, the results indicate that resistin plays a key role in the proliferation and migration of ovarian cancer cells and thus may be useful as a target for treating ovarian cancer." (PMID 34659568, 2021). "In ovarian cancer, there is a previous study investigating the role of resistin." (PMID 30131543, 2018). "Further, 25 ng/mL resistin increased this secretion of VEGF in all the ovarian cancer cells tested." (PMID 30131543, 2018). "We also report that resistin induces resistance against chemotherapy in ovarian cancer cells." (PMID 30131543, 2018). "We also observed that resistin induces stemness in ovarian cancer cells." (PMID 30131543, 2018). "Here, we investigated the hypothesis that resistin regulates ovary carcinoma production of vascular endothelial growth factor (VEGF) and the angiogenic processes." (PMID 23652833, 2013). "Furthermore, resistin accelerates the EMT process in ovarian cancer cells by decreasing the expression of the epithelial cell marker E-cadherin and boosting the expression of the mesenchymal cell markers ZEB1 and Vimentin, thereby encouraging cancer cells to migrate." (PMID 36694280, 2023). "Therefore, resistin shows potential as a molecular therapeutic target in ovarian cancer." (PMID 34659568, 2021). "Furthermore, resistin promoted the migration of ovarian cancer cells." (PMID 34659568, 2021). "Based on the reported involvement of resistin in different cancers, particularly its role in acquired resistance, we hypothesized that resistin might be responsible for similar pro-oncogenic and chemoresistance-inducing functions in ovarian cancer cells as well." (PMID 30131543, 2018).